DDX47 (DEAD-box helicase 47)
Description:
Required for efficient ribosome biogenesis (By similarity). May have a role in mRNA splicing. Involved in apoptosis.
Synonyms: DKFZp564O176; FLJ30012; HQ0256; RRP3; E4-DBP; MSTP162
Tractability: Small molecule: a structure with a bound ligand is known. PROTAC: ubiquitination databases record sites on it; its protein half-life has been measured.
Gene: Protein-coding gene on chromosome 12 (12,813,316 to 12,829,981, forward strand). Ensembl gene ENSG00000213782.
Subcellular location: Nucleus, nucleolus
Subcellular location (Human Protein Atlas): Nucleoli
Pathways (Reactome):
Metabolism of RNA: Major pathway of rRNA processing in the nucleolus and cytosol; rRNA modification in the nucleus and cytosol
Gene Ontology:
Molecular function: protein binding; RNA binding; ATP binding; ATP hydrolysis activity; nucleic acid binding; RNA helicase activity
Biological process: extrinsic apoptotic signaling pathway via death domain receptors; RNA splicing; rRNA processing; ribosome biogenesis
Cellular component: membrane; nucleolus; nucleoplasm; nucleus
Genetic constraint (gnomAD): Loss-of-function variants: 41 observed, 40.55 expected, observed/expected ratio (o/e) 1.01, 90% interval 0.79 to 1.31. The upper end of that interval is the gene's LOEUF score, 1.31, which puts it in group 5 of 6, group 1 being the genes least tolerant of losing a copy. Missense variants: 462 observed, 521.3 expected, observed/expected ratio (o/e) 0.89, 90% interval 0.82 to 0.96. Synonymous variants: 174 observed, 189.65 expected, observed/expected ratio (o/e) 0.92, 90% interval 0.81 to 1.04.
Homologues: Orthologues: macaque DDX47 (99% identical), pig DDX47 (97% identical), dog DDX47 (97% identical), rabbit DDX47 (97% identical), guinea pig DDX47 (97% identical), mouse Ddx47 (96% identical), rat Ddx47 (95% identical), chimpanzee DDX47 (92% identical), tropical clawed frog ddx47 (87% identical), Drosophila melanogaster pths (71% identical), Caenorhabditis elegans T26G10.1 (64% identical), zebrafish ddx47 (47% identical). Paralogues in human: DDX49 (44% identical), DDX27 (35% identical), DDX42 (33% identical), DDX18 (33% identical), DDX23 (33% identical), DDX17 (33% identical), DDX56 (32% identical), DDX10 (32% identical), DDX46 (32% identical), DDX5 (32% identical), DDX43 (31% identical), DDX24 (31% identical), and 26 more.
Diseases named in the same sentence as DDX47 in open-access papers:
DDX47 is named in the same sentence as 8 diseases in open-access papers, as found by Europe PMC text mining. Sharing a sentence is not in itself a finding about the gene and the disease. The quoted sentences say what the papers report.
osteosarcoma (1 paper, 2022). A usually aggressive malignant bone-forming mesenchymal neoplasm, predominantly affecting adolescents and young adults. "In order to determine which lncRNA was involved in osteosarcoma, lncRNAs including lnc-SELPLG-2:1, lnc-DDX47–3:1, lnc-ZNF77–165:3, lnc-SRSF2–9:2, lnc-SAMD11–1:1, and lnc-PPP1R9B-4:2 were detected by RT-qPCR to determine if their sequences were consistent with sequencing results." (PMID 36199080, 2022).
cancer (1 paper, 2023). A tumor composed of atypical neoplastic, often pleomorphic cells that invade other tissues. "Among these, MLF2, COPS7A, PEX5, DDX47, STRAP and MRPL51 displayed strong correlations with USP5 in most cancer types." (PMID 37268697, 2023).
neurodevelopmental disorder (1 paper, 2021). A behavioral and cognitive disorder with onset during the developmental period that involves impaired or aberrant development of intellectual, motor, or social functions. "Two of them (DDX47 and DHX58) are members of the DDX/DHX family, which has recently been implicated in neurodevelopmental disorders." (PMID 33710394, 2021). "DDX47 and DHX58 are members of the DDX/DHX family which has recently been implicated in neurodevelopmental disorders." (PMID 33710394, 2021).
tumor (1 paper, 2021). "DDX47 is involved in maintenance of genome stability via interacting with FANCD2 to lower R-loop levels 28, and study has revealed that overexpression of DDX47 induces tumor cells apoptosis." (PMID 33456353, 2021).
DDX47 also shares sentences with these, for which no sentence is quoted: infection (2 papers); breast carcinoma (1); leukemia (1); virus infection (1).